IRS1 (insulin receptor substrate 1)
Diseases named in the same sentence as IRS1 in open-access papers (continued):
Sharing a sentence is not in itself a finding about the gene and the disease.
type 2 diabetes (continued). "The molecular docking analysis data of beta-caryophyllene with the insulin downstream signaling molecules such as IRS-1 cSrc and Akt reveals its ability and further studies are needed to elucidate its complete mechanism of action against type-2 diabetes." (PMID 35655910, 2021). "For instance, hesperidin upregulated the GLUT2, GLUT4, IRS1 and glucokinase levels and downregulated the hepatic fatty acid oxidation and carnitine palmitoyl transferase activity in type-2 diabetes to improve hyperlipidaemia and hyperglycaemia." (PMID 33926520, 2021). "IRS1 transcription is downregulated in adipose tissue of both rodents and human patients with type 2 diabetes." (PMID 31947955, 2020). "The insulin receptor substrate‐1 (IRS‐1) is a key factor in insulin‐signaling pathways and thus in the development of type 2 diabetes." (PMID 30680172, 2019). "Altered forms of IRS-1 were detected in NDEs of AD plasma patients and at lower levels compared to controls and to patients with type 2 diabetes with intermediate levels." (PMID 31555123, 2019). "Substantial phosphorylation of IRS1 at specific Ser sites occurs in type 2 diabetes- or age-related memory deficits independently of amyloid-β (Aβ)." (PMID 31426549, 2019). "Regulation of ARHGEF11 on IRS1 signaling and the correlation with type 2 diabetes are important for glucose and fatty acid metabolism." (PMID 31612150, 2019). "The expression of miR-29a and miR-29c in skeletal muscle of patients with type 2 diabetes are upregulated which suppresses glucose and lipid metabolism possibly by targeting insulin receptor substrate 1 (IRS1) and phosphoinositide 3 kinase (PI3K)." (PMID 31683538, 2019). "The aim of the current study was to determine the relationship between IRS1 and CCR5 polymorphisms with type 2 diabetes in the Kurdistan population." (PMID 30884193, 2019). "On the other hand, the reduced expression of insulin receptor and IRS-1 of the kidney cortex was proposed to contribute to hyperglycemia in high-fat-diet-fed mice or type 2 diabetic rats." (PMID 31137715, 2019). "Modified Sanzi Yangqin Decoction increases tyrosine phosphorylation of IRS-1 in skeletal muscle of type 2 diabetic rats, which results from the increase of p-IRS-1(Tyr895) protein and is related to the suppression of PTP1B protein." (PMID 29721029, 2018). "This study aimed to investigate the effect of Modified Sanzi Yangqin Decoction on tyrosine phosphorylation of insulin receptor substrate 1 (IRS-1) in skeletal muscle of type 2 diabetic rats." (PMID 29721029, 2018). "We report here a haplotype in the intergenic region between IRS1 and the gene encoding neuronal tyrosine-phosphorylated phosphoinositide-3-kinase adapter 2 (NYAP, KIAA1486) that is protective against IR, type 2 diabetes, and preclinical atherosclerosis." (PMID 26090471, 2015). "The gene-gene interaction between IRS1 Gly972Arg and PPARG Pro12Ala is of interest because the two polymorphisms exert opposite effects on type 2 diabetes predispositions." (PMID 24447396, 2014). "Adipose tissue IRS-1 expression is reduced in humans and animals with type-2 diabetes and in obese subjects." (PMID 24749062, 2014). "This group also explored the regulation of IRS1, active in type 2 diabetes and coronary artery disease, discussing the possible regulatory role of GWAS SNPs in sites 600 Kb and 1 Mb downstream from the IRS1 gene promoter." (PMID 24600475, 2014). "Further, a role for IRS1 in the pathogenesis of type 2 diabetes has been suggested because of differential expression of IRS1 variants." (PMID 26029481, 2013). "The study clearly shows that OI extract is able to prevent, high-fat diet-induced type 2 diabetic manifestations of under-expression of IRS-1 protein and hampered membrane translocation of Glut-4 transporter in the skeletal muscle." (PMID 21785636, 2011).
type 2 diabetes (continued). "Western blot analysis of some proteins involved in insulin-induced glucose metabolism in the muscle tissue in the present study has revealed significantly decreased membrane Glut-4 and cytosolic IRS-1 expressions in high-fat diet-induced type 2 diabetes." (PMID 21785636, 2011). "In hearts of high fat diet-induced type 2 diabetes mice, we also found the expression of myocardin, as well as IRS1, was decreased, providing further evidence for this hypothesis." (PMID 38505620, 2024). "Moreover, oral administration of BAIBA for 4 weeks in type 2 diabetic mice resulted in improved insulin signaling, by restoring Akt-IRS-1 (Tyr632 and Ser307) phosphorylation." (PMID 37780967, 2023). "Therefore, it is of interest to document the molecular dockinganalysis data of beta-Caryophyllene, a naturally occurring sequiterpene with the downstream insulin signaling molecules such as IRS-1, cSrc and Akt for the management of type-2 diabetes." (PMID 35655910, 2021). "Therefore, it is of interest to document the molecular docking analysis data of Beta-Caryophyllene with the downstream insulin signaling molecules such as IRS-1, cSrcand Akt for the management of type-2 diabetes." (PMID 35655910, 2021). "Combining aerobic and resistance training in men and women with type 2 diabetes elicits improvements in fasting and postprandial glucose concentrations, increases in skeletal muscle insulin receptor substrate 1 (IRS-1) protein content, and improvements in muscular strength and hypertrophy." (PMID 32231642, 2020). "Finally, according to the results of this study, it can be concluded that the probability of the positive effect of allele A on the studied polymorphisms IRS1‐rs10498210 G/A and CCR5‐59029 A/G increases the risk of type 2 diabetes." (PMID 30884193, 2019). "The insulin receptor substrate 1 (IRS1) is a critical factor in the signaling pathway for insulin, and mutations in this gene have been reported, which contribute to the ability to develop type 2 diabetes." (PMID 30884193, 2019). "The unbalance between IRS-1 and IRS-2 caused by miR-126 may play an important role in type 2 diabetes." (PMID 26919700, 2016). "The genome wide association studies have identified various susceptibility genes, including several type 2 diabetes mellitus (T2DM) such as PPARG, TCF7L2, FTO, CDKN2A/2B, and IRS1 etc. to be associated with the risk of T2DM, though their definite relation with GDM remains to be explored further." (PMID 28083030, 2016). "Additionally, the associations of MADD, ADRA2A, IRS1 and FASD1 with type 2 diabetes or its related traits were directional different between two subpopulations." (PMID 21747906, 2011). "The direction of associations for loci ADRA2A, IGF1 and IRS1 were consistent to those observed in the previous GWAS, however none of the remaining loci were associated with type 2 diabetes (P≥0.21), IFG (P≥0.10) or combined IFG/type 2 diabetes (P≥0.22)." (PMID 21747906, 2011). "SNPs in or near MADD, ADRA2A, PROX1, FADS1, C2CD4B, IGF1, and IRS1 did not exhibit significant associations with type 2 diabetes or related glycemic traits (P≥0.10)." (PMID 21747906, 2011). "In addition, risk allele of rs2943641 near IRS1 tended to be associated with increase in HOMA-IR further confirming the contribution of this locus with susceptibility to type 2 diabetes in the Japanese." (PMID 22046406, 2011). "Consistent with our results, N-acetylcysteine treatment in type 2 diabetic mice has been shown to effectively preserve the expression of antioxidant enzymes, attenuate ROS production in diabetic ischemic limbs, and reverse the levels of phosphorylated IRS-1, Akt, eNOS, and plasma TNF-α." (PMID 39125400, 2024). "Besides, studies have indicated that baicalein could ameliorate Type 2 Diabetes through the inhibition of the MAPKs pathway and the activation of the IRS1/PI3K/Akt pathway." (PMID 37907988, 2023).
type 2 diabetes (continued). "In contrast, other studies could not demonstrate a deficiency in IRS-1 protein expression in the muscle cells of type 2 diabetes and several other tissues of obese animals." (PMID 36547071, 2022). "Regarding the role of IRS1 in the pathway of insulin signaling and the negative effect of rs10498210 polymorphism on the performance of this protein, it can be expected that this polymorphism is present in the etiology of type 2 diabetes." (PMID 30884193, 2019). "Therefore, our study is the first to illustrate that miR-146b regulates glucose homeostasis in porcine primary pre-adipocytes by targeting IRS1 and it could be a potential target of type II diabetes in the future." (PMID 29522441, 2018). "In Drosophila type 2 diabetes models can be generated by two different strategies: by downregulating conserved genes working on insulin pathways as for example the insulin receptor InR, the insulin substrate receptor chico/IRS1, Akt1, PI3K, and by feeding flies with a high sugar rich diet." (PMID 30271425, 2018). "Recent studies have reported that elevated UA may also reflect oxidative stress and systemic inflammation and is closely related with the pathogenesis of IFG and type 2 diabetes that impairs insulin receptor substrate 1 and Akt insulin signaling in the liver, skeletal muscle, and adipose tissue." (PMID 30008811, 2018). "Type 2 diabetes was negatively associated with IKKβ, IRS1 and JNK among participants without dementia; whereas among participants with dementia and AD pathology, a significant negative association was observed with IRS1 and PKR, and a significant positive relationship with JNK." (PMID 27106634, 2017). "In type 2 diabetes, receptor activation and recognition by microorganisms from the intestinal lumen may trigger inflammatory responses, inducing the phosphorylation of serine residues in insulin receptor substrate-1, reducing insulin sensitivity." (PMID 24939063, 2014). "Similarly, the Gly > Arg mutation (Gly97Arg) of the insulin receptor substrate 1 (IRS1) is associated with a 15% increased risk of type 2 diabetes, although the difference is not significant." (PMID 19390629, 2009). "Nrf2 (p < 0.0001), total IRS-1 (p < 0.01), p-IRS-1(p < 0.0001), p-Akt (p < 0.0001)and PI3K p85 (p < 0.0001) proteins were significantlysuppressed in the livers of type 2 diabetes-induced animals." (PMID 40547654, 2025). "In the study on human type II diabetes, RSG improved glucose utilization, promoted the expression of IRS‐1 and GLUT‐4, and improved insulin sensitivity." (PMID 33650786, 2021). "For instance, SOCS1 degrades IRS1 and IRS2, required for insulin signaling, via the SOCS Box domain, thus, limiting its potential in type-2 diabetes." (PMID 31105556, 2019). "Studies revealed an impaired insulin-stimulated phosphorylation of IRS-1 and a decrease of PI3K activity in the muscle from obese and type 2 diabetes." (PMID 31847151, 2019). "Protein tyrosine phosphatase (PTP-1B), is a negative regulator of insulin signaling; it inhibits insulin-stimulated tyrosine phosphorylation of insulin receptor (IR), insulin receptor substrate-1 (IRS-1) and is a therapeutic target for type 2 diabetes." (PMID 28608836, 2017). "IRS1 SNPs were identified and analysed in Mexican-American individuals, to identify links between declining GFR and type 2 diabetes." (PMID 27514532, 2016). "The levels of a number of insulin signaling molecules including IR, IRS-1, and PKB were significantly reduced in the post-mortem frontal cortex of individuals with both AD and type II diabetes." (PMID 26499801, 2015). "While CGA itself does not impact the phosphorylation of phosphatidylinositol 3-hydroxykinase (PI3K) and insulin receptor substrate (IRS-1), its metabolites can phosphorylate PI3K and IRS-1, leading to increased insulin sensitivity and a beneficial effect on type 2 diabetes." (PMID 38921480, 2024).
type 2 diabetes (continued). "It is worth mentioning that the combined effects of low-molecular-weight fucoidan (LMWF) and fucoxanthin dramatically enhanced the overexpression of insulin receptor substrate-1 (IRS-1) and glucose transporter type 4 (GLUT4) in a mouse model of type II diabetes (T2D)." (PMID 38248653, 2023). "Results from a proteomic study assessed IRS-1 protein interactions in skeletal muscles from normal individuals, obese insulin-resistant nondiabetic control subjects, and patients with type 2 diabetes, before and after insulin infusion." (PMID 34183055, 2021). "On the contrary, the flavonoid myricetin up-regulated p-IR, p-IRS1 and p-AKT in the liver of HFD-fed and STZ-induced type 2 diabetic rats by inhibiting the activity and expression of PTP1B, the tyrosine phosphatase that negatively regulates the insulin signal transduction." (PMID 34208379, 2021). "This is interesting because NDEs IRS-1 protein levels could contribute to discriminate MCI/AD to controls and patients with type-2 diabetes at the same time." (PMID 31555123, 2019). "In this regard, the relationship between the IRS1‐rs10498210 G/A polymorphisms and CCR5‐59029 A/G and the risk of type 2 diabetes have not been clearly and precisely indicated." (PMID 30884193, 2019). "Given their central role in the insulin signalling pathway, it is not surprising that male mice lacking Irs1 or Irs2 present with elevated blood glucose or type 2 diabetes, respectively." (PMID 27514532, 2016). "Proinflammatory cytokines, such as tumor necrosis factor alpha (TNF-α) and IL-6, generated during the innate response, can inhibit insulin signaling through the phosphorylation of insulin receptor substrate 1 (IRS-1), serving to link inflammation with IR and type 2 diabetes." (PMID 26458065, 2015). "Irs1−/− have mild glucose intolerance and Irs3−/− have no detectable phenotype, but Irs1−/−/Irs3−/− are hyperglycemic and display severe lipoatrophy, indicative of their interaction in developing the type 2 diabetes phenotype." (PMID 25825681, 2015). "Sites annotated to 10 candidate genes for type 2 diabetes, including DUSP9, BCL11A, HNF4A, and CDKN2B, and 7 candidate genes for related metabolic traits (for example, ATP11A, ADCY5 and IRS1) had differential DNA methylation in human pancreatic islets based on sex." (PMID 25517766, 2014). "While the IR isoform A to B as well as the IRS-1 to IRS-2 ratios were not different in patients with type 2 diabetes, we found IGF-1 receptor to be reduced in this patient group." (PMID 23251408, 2012). "IRS1 null mice have much reduced growth (30-60% of control), whereas IRS2 null mice have almost normal growth (about 90% of control), but develop type 2 diabetes, therefore IRS1 is thought to be downstream of the IGF1 receptor, and IRS2 downstream of the insulin receptor." (PMID 21798082, 2011). "However, other studies demonstrated that even total ablation of IRS-1 is not sufficient to induce type II diabetes in mice." (PMID 39355613, 2024). "In the Type 2 diabetic rat model induced by HFD and low-dose of STZ, biotin supplementation exerted antioxidant, anti-hyperlipidaemic, anti-inflammatory and anti-hyperglycaemic effects, increasing the level of insulin, probably through modulation of PPAR-γ, IRS-1 and NF-κB proteins." (PMID 28574454, 2017). "TRB3 is upregulated in the skeletal muscle of patients with Type II diabetes and TRB3 over-expression in muscle cells blocks insulin-stimulated glucose transport and impairs phosphorylation of AKT, extracellular-signal regulated kinase (ERK), and insulin receptor substrate-1 (IRS1)." (PMID 24490110, 2013).
type 2 diabetes (continued). "However, we found diminished basal serine-632 IRS-1 phosphorylation in obese muscle, and insulin only mildly activated serine phosphorylation, compared to unstimulated obese, as opposed to previous studies showing the hyperphosphorylation of serine-632 IRS-1 in the muscle cells of type 2 diabetes." (PMID 36547071, 2022). "Because IRS1 signaling is essential for glucose homeostasis in liver, and is related with the insulin sensitivity and resistance, it is likely that this SNP may affect the function of DRE, which may impact the expression of IRS1 and contribute to type II diabetes." (PMID 24003029, 2013). "As far as we know, two previous studies in humans, with small sample size (n = 39–40), examined protein or gene expression of the IGF1, IGF2, IGFBP3, INSR, IGF1R and downstream targets IRS1, IRS2 and mTOR in women with or without type 2 diabetes." (PMID 29486734, 2018).